CTLA4 (cytotoxic T-lymphocyte associated protein 4)
Diseases named in the same sentence as CTLA4 in open-access papers (continued):
Sharing a sentence is not in itself a finding about the gene and the disease.
head and neck squamous cell carcinoma (continued). "Moreover, transfection of miR-21-5p has also been reported to significantly elevate the expression levels of CTLA-4 and LAG3 miRNA in head and neck squamous cell carcinoma." (PMID 36765782, 2023). "The antitumor effect of immune checkpoint inhibitors (ICIs) such as antibodies against CTLA-4, PD-1, and PD-L1 is higher than that of conventional chemotherapy and is durable, improving the survival of patients with advanced head and neck squamous cell carcinoma (HNSCC)." (PMID 35159059, 2022). "The clinical application of immune checkpoint blockade (ICB), via monoclonal antibodies blocking PD-1/PD-L1 and CTLA4, has achieved promising durable therapeutic response in various cancer types, including recurrent and metastatic head and neck squamous cell carcinomas (HNSCC)." (PMID 33403469, 2021). "Besides PD-L1, PD-L2, PD-1, CD80, CD86, CTLA-4, Tim-3, LAG3, and 4-1BB, we found the increase of an inducible co-stimulator (ICOS) expression in both HPV-positive head and neck squamous cell carcinoma and EBV-positive stomach adenocarcinoma tumors." (PMID 30911684, 2019). "Overall, PD-1 and CTLA-4 are overexpressed in OSCC tumors with high T cell infiltration, mirroring observations in human head and neck squamous cell carcinoma (HNSCC) and represent promising immunotherapeutic targets." (PMID 41230456, 2025). "Therapeutic strategies for head and neck squamous cell carcinoma (HNSCC) have undergone a paradigm shift from chemotherapy, radiotherapy, and targeted therapy to immunotherapy, through the targeting of tumor cells and immune checkpoints (PD-1, PD-L1, and CTLA4)." (PMID 38519500, 2024). "In contrast, anti-CD73 Abs significantly downregulated the expression of PD-1 and CTLA-4 by CD4+ and CD8+ T cells in a murine transgenic head and neck squamous cell carcinoma (HNSCC) model, resulting in substantial reduction of tumor growth." (PMID 35711418, 2022). "ICB targets immune checkpoints, such as the CTLA-4 or the PD-1/PD-L1 axis with specific antibodies, and has achieved significant results in several cancer entities, including melanoma, non-small cell lung cancer (NSCLC), and squamous cell carcinoma of the head and neck (HNSCC)." (PMID 32899762, 2020). "This synergistic effect between EVO and ICIs has also been observed in other tumor types, such as head and neck squamous cell carcinoma (HNSCC), where the combination of EVO and anti-CTLA-4 therapy significantly improved survival compared to immunotherapy alone." (PMID 40710312, 2025). "Another checkpoint inhibitor, anti-CTLA-4 mAb Ipilimumab, is used in combination with non-engineered allogeneic CIML NKs in head and neck squamous cell carcinoma (HNSCC) patients (row 26)." (PMID 36348457, 2022).
mesothelioma (61 papers, 2013 to 2025). A usually malignant and aggressive neoplasm of the mesothelium which is often associated with exposure to asbestos. "Immunotherapies targeting immune checkpoint molecules such as PD-1 (programmed cell death 1), PD-L1 (programmed cell death 1-ligand 1), and CTLA-4 (cytotoxic T-lymphocyte-associated antigen 4) may be effective treatments for mesothelioma." (PMID 40002287, 2025). "Moreover, the association of anti-CTLA-4 agents with gemcitabine in a murine mesothelioma model, proved to have a synergistic effect against tumor growth." (PMID 34199722, 2021). "The current FDA-approved combination treatment of PD-1 and CTLA-4 has been proven to extend mesothelioma patient survival beyond those treated with chemotherapy." (PMID 39939955, 2025). "The recent approval of combined immunotherapy that targets PD-1 and CTLA-4 has altered the clinical management of mesothelioma." (PMID 40707702, 2025). "According to these findings, the use of intra-tumoral SS1P in combination with anti-CTLA-4 warrants future investigations in mesothelioma patients." (PMID 40918456, 2025). "While the introduction of immunotherapy combinations using ipilimumab (anti-CTLA-4) and nivolumab (anti-PD-1) have offered hope for some patients, a large proportion of mesothelioma cases, particularly the epithelial subtype, have minimal benefit from this." (PMID 39939955, 2025). "The CTLA-4 inhibitor tremelimumab was one of the first ICIs trialed for mesothelioma in the MESOT-TREM-2008 study." (PMID 40002287, 2025). "In a murine mesothelioma model, CTLA4 blockade reduced the proportion of Treg cells relative to effector T cells after radiation, boosting the activation of CD8 + T cells." (PMID 38589494, 2024). "The CTLA4 inhibitor tremelimumab was the first immune checkpoint inhibitor assessed in mesothelioma." (PMID 36776840, 2023). "Previously, meticrane in combination with CTLA-4 treatment was reported to improve the survival of mesothelioma mice, however, the anticancer effect of meticrane in tumors remained unexplored." (PMID 37274234, 2023). "Another study assessing a similar schedule of 5 Gy x 3 followed by anti-CTLA-4 in the AE17 model of mesothelioma found significantly smaller tumors following combined treatment compared to either treatment alone." (PMID 36387076, 2022). "The anti-CTLA-4 treatment, tremelimumab, has been investigated as single agent in two phase II trials in pre-treated mesothelioma patients." (PMID 36551550, 2022). "To assess anti-tumor responses of chemotherapy when combined with ICB in vivo, we screened 10 chemotherapeutics from different canonical classes in combination with anti‐CTLA‐4/anti‐PD-L1 antibodies in two murine mesothelioma models." (PMID 35634282, 2022). "In one study using the AB12 murine mesothelioma model, hypo-fractionated RT (5 Gy x 3) followed by anti-CTLA-4 antibody led to abscopal effects, increased T cell infiltration, and increases in immune-related gene expression and cytokine production." (PMID 36387076, 2022). "Prior to Checkmate-743, several earlier trials had tested CTLA4, PD-1 and PD-L1 antagonists for relapsed mesothelioma, with adoption of dual immune checkpoint blockade into treatment guidelines." (PMID 35130961, 2022). "Previously, we identified that combination therapy of retinoic acid and anti-CTLA4 antibody was highly efficacious in a mesothelioma mouse model." (PMID 35402250, 2022). "Initial monotherapy studies with the anti-CTLA-4 agent tremelimumab opened the field of ICI therapy in second line mesothelioma patients." (PMID 34301276, 2021). "In several murine mesothelioma models blockade of immune suppressive CTLA-4 resulted in therapeutic effects when administered alone, or when combined with chemotherapy or radiation." (PMID 34199722, 2021). "When anti-CTLA-4 was administered alone in mesothelioma-bearing mice, it inhibited tumor growth and increased overall survival." (PMID 34199722, 2021).
mesothelioma (continued). "In this scenario, very limited clinical benefit was demonstrated in mesothelioma patients treated in monotherapy with the anti-CTLA-4 mAb tremelimumab or the PD-1/PD-L1." (PMID 32033266, 2020). "To this end, in this study, we investigated this molecule in a cohort of mesothelioma patients treated with the anti-CTLA-4 mAb tremelimumab combined with the anti-PD-L1 mAb durvalumab, within the NIBIT-MESO-1 trial (NCT02588131)." (PMID 32033266, 2020). "In a dual murine model of mesothelioma, left (primary tumor) and right flanks (secondary tumor), combining 5 Gy local γ‐irradiation with anti‐CTLA‐4 antibody, increased antitumor effects over either single agent." (PMID 32994997, 2020). "We therefore applied mMCP-counter to pre-treatment samples of mouse models of kidney cancer and mesothelioma that have been treated with a combination of CTLA-4 and PD-L1 blockade." (PMID 33023656, 2020). "We first examined publicly available mRNA expression data from a study in which immunocompetent mice were inoculated with bilateral s.c. murine AB1-HA mesothelioma tumors and treated with an anti–CTLA-4 antibody." (PMID 29618661, 2018). "For instance, systemic blockade of immune checkpoints such as CTLA-4, PD-1 and its ligands PD-L1/2 has shown significant antitumor effects in certain cancers including mesothelioma." (PMID 29699510, 2018). "We previously demonstrated that blockade of immune suppressive CTLA-4 resulted in tumor growth delay when combined with chemotherapy in murine mesothelioma." (PMID 25980578, 2015). "Here, we provide proof of concept for the validity of this approach in a murine mesothelioma model, which displays a dichotomous response to anti-CTLA4 immune checkpoint blockade." (PMID 26193793, 2015). "Most notably, immune checkpoint blockades (ICBs) targeting PD-1/PD-L1 and CTLA-4 have shown clinical activity in mesothelioma, leading to the approval of nivolumab (NIVO) (anti-PD-1) plus ipilimumab (IPI) (anti-CTLA-4) as a first-line option for unresectable PM." (PMID 41463268, 2025). "Combination therapies involving a PD-1 inhibitor and a CTLA-4 inhibitor or kinase-targeting therapies are gaining traction as viable strategies to treat mesothelioma, so much so that one of the combinations was approved for clinical use as a first-line therapy." (PMID 40002287, 2025). "Mesothelioma cells are known to develop mechanisms for escaping immune surveillance, leading to T cell exhaustion via up-regulation of immune checkpoint molecules such as CTLA-4." (PMID 34830817, 2021). "Besides, the frequencies of Tregs – plus the ratio of Tregs to CD8+ T cells – were increased in the primary and secondary tumors 7 days after radiotherapy; this phenomenon was regulated by CTLA‐4 blockade in a mesothelioma model." (PMID 32994997, 2020). "Accordingly, our phase II NIBIT-MESO-1 study demonstrated an improved clinical efficacy in mesothelioma patients treated with the anti-PD-L1 durvalumab combined with the anti-cytotoxic T-lymphocyte antigen (CTLA)-4 tremelimumab, as compared to tremelimumab alone." (PMID 32033266, 2020). "By contrast, the CTLA-4 expression positively correlates with less advanced stage, intestinal type and well/moderately differentiated gastric adenocarcinoma and represents a favorable prognostic factor in mesothelioma tissues, serum and pleural effusion." (PMID 29682176, 2018). "Altogether, this study shows that the local administration of anti-mesothelin immunotoxins potentiates the effect of anti-CTLA-4 in a murine mesothelioma model and induces markers of immunogenic cell death, providing preclinical support to pursue this combination strategy in the clinic." (PMID 30441807, 2018). "Evidence in our AB12 mesothelioma model indicated that systemic blockade of the immune checkpoints CTLA-4 and PD-1 in combination with chemo- or radiation therapy did result in tumor growth delay through enhancing antitumor immunity, such as activating T cells and decreasing Treg." (PMID 29699510, 2018).
mesothelioma (continued). "Indeed, following anti-CTLA4 therapy in the mesothelioma model, NOS2 activity was identified as an important hub for efficacy." (PMID 26861383, 2016). "We studied the abscopal effect induced by LRT with γ-ray irradiation in murine mesothelioma model and determine if this effect could be promoted by removing the immunosuppressive CTLA-4 signal." (PMID 25980578, 2015). "Recently, Wu and colleagues found that anti-CTLA-4 treatment in combination with cisplatin resulted in better disease control in a murine mesothelioma model, when tumors were treated before they were palpable, presumably due to inhibited cancer cell repopulation." (PMID 23626745, 2013). "Then, because the combination of tumor vaccine and ICIs reported benefits in clinical and pre-clinical trials for cancer therapy, the hypothesis of the sPD-1-TWIST1 vaccination combined with anti-CTLA-4 was also tested, resulting in elicited long-lasting T cell immunity and mesothelioma reduction." (PMID 34830817, 2021). "In an epithelioid mesothelioma model, anti-PD-1 plus anti-TIGIT induced stronger and more durable anti-tumor responses than either chemotherapy or dual anti-PD-1 plus CTLA-4 therapy." (PMID 41463268, 2025). "In the bilateral tumor model, we excised one flank tumor before (day 0), or 2, 4 or 6 days after anti-CTLA-4 and anti-PD-L1 treatment for bulk TCRβ sequencing in two mouse models, AB1 mesothelioma and RENCA renal cancer." (PMID 38686178, 2024). "When CTLA-4, OX40 or GITR are individually targeted, it generates efficient responses against mesothelioma." (PMID 34267616, 2021). "In Immune Checkpoint Blockade (ICPB)-treated mice, anti-CTLA-4+ anti-OX40-based treatments induce powerful and durable responses in orthotopic and subcutaneous mesothelioma tumor model." (PMID 34267616, 2021). "In the mesothelioma animal model treated with anti‐PD1 and anti‐CTLA4, we revealed that a lower expression of most rhythm genes predicts response to combined ICB therapy." (PMID 31927791, 2020). "More recent mesothelioma immunotherapy trials such as KEYNOTE-028 (anti-PD-1) and IFCT-1501 MAPS2 (anti-PD-1 monotherapy or combined with anti-CTLA-4) have excluded patients with a peritoneal primary site." (PMID 30914057, 2019). "We then demonstrate in a mouse model of mesothelioma that the combination of anti-PD-1 and anti-TIGIT elicits an enhanced anti-tumour response compared to clinical standard-of-care therapies (anti-PD-1 + CTLA-4 combination and chemotherapy)." (PMID 39939955, 2025). "CTLA-4 or CD152, is an immune system checkpoint receptor which downregulates immune system response by limiting co-stimulation, activation and subsequent proliferation of T cells through competition against the normal co-stimulatory signal and were first studied in mesothelioma." (PMID 32942580, 2020). "In this consideration, besides anti-PD-1, other immune checkpoint inhibitors such as anti-BTLA, anti-CTLA-4, anti-Siglec-10, anti-TIGIT, anti-TIM-3, anti-LAG-3 could be tested in combination to investigate their suitability for enhancing Vδ2 T cell efficacy in this mesothelioma model." (PMID 38077396, 2023). "Comparable results have been obtained with in vivo syngeneic mesothelioma models treated with vinorelbine or 5-fluorouracil and dual PD-1/CTLA4 blockade, with AB1 (but not AE17) mesothelioma revealing some degree of antagonism." (PMID 39653769, 2025).
Graves disease (59 papers, 2004 to 2025). Graves' disease is an autoimmune disorder that leads to overactivity of the thyroid gland (hyperthyroidism).It is caused by an abnormal immune system response that causes the thyroid gland to produce too much thyroid hormones. "Previous studies have suggested that CTLA-4 is implicated in the pathogenesis of Graves’ disease and that PD-L1 expression is elevated in Hashimoto’s hypothyroidism." (PMID 40529668, 2025). "CTLA-4 gene polymorphisms have been linked to both Graves’ disease and TED, supporting a potential pathogenic role." (PMID 41441522, 2025). "Some previous research has linked this LD block in CTLA4 with immune-related diseases, such as Graves’ disease and Rasmussen syndrome." (PMID 38723011, 2024). "In contrast to Grave’s disease, CD exhibits distinct correlations at the CTLA4 exon 1 single nucleotide polymorphism (SNP) +49G>A." (PMID 35911325, 2022). "Polymorphism of CTLA-4 is known to increase the risk of autoimmune susceptibility including Graves’ disease, but how it interacts with ICPis is unclear." (PMID 33920721, 2021). "Sporadic cases of Graves’ disease and thyroid ophthalmopathy have been described in association with anti-CTLA-4 treatment." (PMID 33228219, 2020). "A meta-analysis reported polymorphism of CTLA-4 can increase the risk for Graves’ disease but how this interacts with ICI is unclear." (PMID 30693099, 2019). "We conducted a case/control study to assess the impact of SNP rs3087243 and rs231775 within the CTLA4 gene, on the susceptibility to Graves' disease (GD) in a Chinese Han dataset (271 cases and 298 controls)." (PMID 29299173, 2017). "Polymorphism of -318 C/T (rs5742909) of the CTLA4 gene in adult Graves disease, pediatric Graves disease, Hashimoto disease patients and controls." (PMID 27111218, 2016). "Polymorphism of CT60 (rs3087243) of the CTLA4 gene in adult Graves disease, pediatric Graves disease, Hashimoto disease patients and controls." (PMID 27111218, 2016). "Polymorphism of +49A/G (rs231775) of the CTLA4 gene in adult Graves disease, pediatric Graves disease, Hashimoto disease patients and controls." (PMID 27111218, 2016). "Since then, many studies have evaluated the CTLA-4 polymorphism in different ethnic groups and its association with ophthalmopathy and Graves' disease." (PMID 25653477, 2015). "Many studies have established that T-lymphocyte antigen-4 (CTLA4) is a susceptible gene for Graves' disease (GD)." (PMID 25121088, 2014). "Most genes that have been associated with AITD (predominantly Graves' disease) by candidate gene and GWAS studies so far are located in the HLA class I and II regions, or in genes involved in T-cell (i.e., CTLA-4, PTPN22) or other autoimmune responses." (PMID 24586183, 2014). "After reading the titles and abstracts, 302 results were excluded for being irrelevant to CTLA-4 polymorphisms and Graves’ disease risk, abstracts, reviews or duplications of search results." (PMID 23597029, 2013). "The associations between the polymorphisms in Cytotoxic T lymphocyte-associated molecule-4 (CTLA-4) gene and Graves’ disease (GD) have been extensively investigated in Chinese population." (PMID 23597029, 2013). "The +49A/G polymorphism of the cytotoxic T-lymphocyte-associated antigen-4 gene (CTLA-4) has been associated with Graves’ disease (GD)." (PMID 23181132, 2012). "Another study published in 2007 demonstrated a very strong causal relationship between 49A/G polymorphism of CTLA-4 gene and the development of Hashimoto Thyroiditis (HT) and the presence of anti-thyroid antibodies in Graves’ disease and HT." (PMID 23072316, 2012). "In Graves' disease, a specific CTLA-4 polymorphism has been associated with an early age of onset and severity of presentation." (PMID 22099887, 2011). "Graves’ disease: CTLA4 and PTPN22 variants are linked to Graves’ disease." (PMID 39726471, 2024).